EXT2 (exostosin glycosyltransferase 2)
Diseases named in the same sentence as EXT2 in open-access papers (continued):
Sharing a sentence is not in itself a finding about the gene and the disease.
femoral neck fracture (1 paper, 2024). Fractures of the short, constricted portion of the thigh bone between the femur head and the trochanters. "The immunohistochemical expressions of SDC1, SDC2, SDC4, EXT1, EXT2, NDST1 and NDST2 in synovial intima and subintima were then analysed and compared with the control group (patients with femoral neck fracture)." (PMID 38674142, 2024).
heart failure (1 paper, 2022). Inability of the heart to pump blood at an adequate rate to meet tissue metabolic requirements. "We found that significant upregulation of EXT1 and EXT2 was closely associated with cardiac fibrosis and heart failure in DCM, which partly explained the potential molecular mechanism of HS biosynthetic activation in DCM." (PMID 35711374, 2022).
Hepatitis (1 paper, 2023). Inflammation of the liver. "In addition, an increased abundance of CS and HS delayed the regenerative process from CCl4-induced hepatitis in EXT2–/– mice." (PMID 37567982, 2023).
ischemic disease (1 paper, 2015). Lack of blood supply to an area of the body, resulting in impairment of tissue oxygenation. "Altogether, these data indicate that EXT2, HPSE, and SDC-4 are involved in the proangiogenic effects of LMWF, suggesting that the HS metabolism changes linked to LMWF-induced angiogenesis offer the opportunity for new therapeutic strategies of ischemic diseases." (PMID 26516869, 2015).
malignant glioma (1 paper, 2026). A grade III or grade IV glioma arising from the central nervous system. "In contrast to EXT1, EXT2 was predominantly expressed in malignant glioma cell populations, particularly those enriched in mesenchymal and contractile gene signatures." (PMID 41438585, 2026).
microcephaly (1 paper, 2026). A congenital or acquired developmental disorder in which the circumference of the head is smaller than normal for the person's age and sex. "EXT2, for instance, is a glycosyltransferase deregulated in EXT2-related syndrome, where one of the manifestations of the disease is microcephaly, a phenotype partially recapitulated in zebrafish embryos microinjected with DplUSE RNA." (PMID 41505098, 2026).
multiple myeloma (1 paper, 2013). "In particular, EXT2 has been identified in earlier studies as a glycome gene differentially expressed in myeloma cells as compared to normal plasma cells which may have a crucial role in multiple myeloma growth development." (PMID 24386263, 2013).
myeloma (1 paper, 2013). "Enzymes relevant for the initiation of GAG formation and heparan sulfate chain elongation, beta-1,3-glucuronyltransferase 3 (B3GAT3), multiple exostosin-like 2 (EXTL2) and EXT2 heparan sulfate copolymerase (EXT2), display enhanced expression in myeloma cells." (PMID 24386263, 2013).
non-small cell lung carcinoma (1 paper, 2023). A group of at least three distinct histological types of lung cancer, including non-small cell squamous cell carcinoma, adenocarcinoma, and large cell carcinoma. "Another study reported that germline variants (p.W606X, IVS1762-1G > A, p.T507fs, and p.T642fs) in EXT2 were found in 4 out of 1026 patients with non-small cell lung cancer." (PMID 37461096, 2023).
Noonan-like syndrome (1 paper, 2024). "During our study, patients with Noonan-like syndrome (SHOC2 gene mutation), mitochondrial pathology, and EXT2 gene variant showed distinctive treatment responses." (PMID 39529965, 2024).
oligodendroglioma (1 paper, 2026). A well-differentiated (WHO grade II), diffusely infiltrating neuroglial tumor, typically located in the cerebral hemispheres. "EXT1 and EXT2 were particularly enriched in recurrent GBM and oligodendrogliomas, consistent with EXT1's vascular-stromal localization and EXT2's mesenchymal distribution." (PMID 41438585, 2026).
papillary thyroid carcinoma (1 paper, 2025). "One case of papillary thyroid carcinoma was described in a 36-year-old man from the Netherlands; no EXT1 or EXT2 mutations were identified." (PMID 41441317, 2025).
Sepsis (1 paper, 2025). Sepsis is defined as life-threatening organ dysfunction caused by a dysregulated host response to infection. "The results showed that, compared with the healthy control group, the expression of EXT1, HIF1A and HMMR was upregulated in sepsis, whereas the expression of CD44, EXT2 and SELL was downregulated in sepsis group." (PMID 40672940, 2025).
synovitis (1 paper, 2024). Inflammation of a synovial membrane. "SDC1, SDC4, NDST1 and EXT2 seem to be involved as inflammation moderators in low-grade OA synovitis and, therefore, should be further investigated as potential markers of disease progression and therapeutic goals." (PMID 38674142, 2024). "Still, we concluded that syndecans (SDC1, SDC4), exostosins (EXT2) and sulfotransferases (NDST1) play a role in the progression and control of synovitis and, consequently, are potential therapeutic targets." (PMID 38674142, 2024). "Therefore, our data provide more information in support of syndecan (SDC1, SDC4), exostosin (EXT2) and sulfotransferase (NDST1) involvement in the progression and control of synovitis." (PMID 38674142, 2024). "According to our study, the immunoexpression of SDC1, NDST1 and EXT2 is significantly increased in the intimal cells of OA synovial membrane in patients with lower histological synovitis scores and SDC4 in patients with higher synovitis scores, in comparison with non-OA controls." (PMID 38674142, 2024).
tumor (24 papers, 2008 to 2026). "This disorder is associated with loss-of-function mutations in the EXT1 and EXT2 genes, which are considered tumor-suppressor genes." (PMID 40390716, 2025). "By contrast, germline mutations concerning the EXT2 gene, which is involved in heparan sulphate biosynthesis and in tumor suppression, appear to be associated with hereditary multiple exostosis (HME), an autosomal dominant disease." (PMID 36673024, 2023). "EXT1 and EXT2 are tumor suppressor genes that encode glycosyltransferases involved in the biosynthesis of heparan sulfate." (PMID 35955863, 2022). "Both genes that encode exostosin glycosyltransferases (EXT1 and EXT2) function as tumor‐suppressors, although the molecular mechanisms and prognostic value of exostosins (EXTs) in cancer is still unclear." (PMID 33314711, 2021). "In almost 90% of MO patients germline mutations in the tumour suppressor genes EXT1 or EXT2 are found." (PMID 18271966, 2008). "Both genes (EXT1 and EXT2) encoding exocrine glycosyltransferases have tumor-suppressive functions, although the details of mechanisms and predictions of the prognostic value of exostosin in cancer remain unclear." (PMID 38293671, 2023). "Additional enrichment in complement and inflammatory response pathways further suggests that EXT2 contributes to a pro-invasive and immune-modulatory tumor phenotype." (PMID 41438585, 2026). "Pathway enrichment terms including “Actin cytoskeleton organization”, “Stress fiber assembly”, and “Cell-substrate adhesion” were strongly overrepresented, reinforcing EXT2's role in tumor cell migration, plasticity, and ECM interactions." (PMID 41438585, 2026). "Germline heterozygous loss-of-function mutations in the EXT1 (exostosin-1, located on chromosome 8q23-q24) or EXT2 (exostosin-2, located on chromosome 11p11-p12) tumor suppressor genes are responsible for over 70–95% of HME cases." (PMID 33632255, 2021). "Pearson Correlation Analysis of gene expression among the 21 tumor samples revealed that EXT1 showed strong correlation to all the other enzymes (r > 0.8 for EXT2, NDST1, and HS6ST1)." (PMID 33585200, 2020). "Nonetheless, several genes significantly increase in tumors and impact patient survival (XYLT2, B3GAT3, EXT2) while HS3ST1 is decreased in tumor." (PMID 33585200, 2020). "Previous studies on the genetic linkage for this disease reported some loci on the chromosomes, with mutation analyses identifying two genes as tumor suppressors: exostosin 1 (EXT1) and exostosin 2 (EXT2)." (PMID 32843889, 2020). "All four genes (EXTL2, EXTL3, EXT1, and EXT2) involved in elongation of the backbone of HS chains are significantly >2-fold upregulated in tumor compared to the adjacent benign tissues." (PMID 33585200, 2020). "This supports the hypothesis that genetic factors other than EXT1 or EXT2 mutations, such as CDKN2A, are involved in tumor progression." (PMID 32295254, 2020). "Based on these findings, EXT2 is discussed as a putative tumor suppressor." (PMID 22194956, 2011). "Furthermore, the absence of genetic testing for EXT1/EXT2 mutations and inflammatory marker analysis limits a more detailed understanding of the tumor’s pathogenesis." (PMID 41181450, 2025). "In addition, two factors of RAS signaling pathways, GRB2 and DUSP6, may be involved in the invasiveness of circulating tumor cells through intricate interactions with the suppressor gene EXT2." (PMID 36672653, 2023). "Starting from our previous study on the comparison of the genomic profiles of matched tumour core and PBZ biopsies, we selected CDK4 and EXT2 as putative malignant drivers of PBZ." (PMID 36769158, 2023). "In Grade II-III tumours, there was a 4-fold decrease in the EXT1 expression level, though the EXT2 expression was maintained, whereas in GBM tissues (Grade IV) the EXT2 expression level was decreased by 3–4-fold as well (p < 0.05)." (PMID 29104277, 2017).
tumor (continued). "Several other genes synthesizing the HS chains are upregulated in tumor tissues, and groups of the genes (e.g. EXT1, EXT2, and SULF2) may be jointly regulated in the tumor tissues." (PMID 33585200, 2020). "EXT1, EXT2, and SULF2 are probably co-upregulated in tumor tissues according to the correlation analysis and higher gene expression in SULF2-positive tumors than in SULF2-negative tumors, but the mechanism underlying such upregulation still needs to be further explored." (PMID 33585200, 2020). "However, EXT2 expression levels were not significantly different between tumor and normal tissues." (PMID 33314711, 2021).
cancer (19 papers, 2014 to 2026). A tumor composed of atypical neoplastic, often pleomorphic cells that invade other tissues. "Previous studies have established associations between the genetic dysregulation of EXT2 and cancer." (PMID 40234611, 2025). "Another two probands carried likely pathogenic variants of other genes known to be associated with a genetic predisposition toward cancer (EXT2 = 1, ERCC2 = 1)." (PMID 34567566, 2021). "To evaluate the clinical relevance of EXT1 and EXT2 in the context of therapeutic responses, we analyzed drug sensitivity correlations using the Genomics of Drug Sensitivity in Cancer (GDSC) database." (PMID 41438585, 2026). "Further analysis of the expression of Ext1 and Ext2 in cancer cells and fibroblasts is needed to gain a better understanding of how TME with Ext1 loss of fibroblasts can lead to cancer development." (PMID 36809261, 2023). "However, the translational potential of EXT2 targeting in its connection to SAM is high based on the known functions of SAM in both cancer and normal cells, possibly due to its role as a major methyl donor and epigenetic regulator." (PMID 40234611, 2025). "Notably, the role of EXT2 in cancer metabolism has remained largely unexplored." (PMID 40234611, 2025). "The expression of EXT2 and EXTL3 was reduced in all cancer cell lines whereas EXTL2 was down-regulated in MCF7 cells but highly up-regulated in MDA-MB-231, and HCC38." (PMID 30054430, 2018). "Transcriptional patterns of HS-metabolic enzymes (EXT1, EXT2, NDST1, NDST2, GLCE, 3OST1/HS3ST1, SULF1, SULF2, HPSE) were determined in normal, benign, and cancer human prostate tissues and cell lines (PNT2, LNCaP, PC3, DU145)." (PMID 24782989, 2014). "Furthermore, these results, pointing out the cancer-promoting role of CDK4 and EXT2 specifically in GBM, allowed the contemplation of a similar function also in the PBZ." (PMID 36769158, 2023). "Data from the The Cancer Genome Atlas (TCGA) and Genotype Tissue Expression (GTEx) database, consulted by OncoDB, showed that CDK4 and EXT2 mRNA expression increased with malignancy augmentation, rising from normal brain tissue, passing through LGG, ending in GBM." (PMID 36769158, 2023). "Two CNVs (chromosome 8q24.22-q24.3 and 11p11.2-p12 deletion) encompassed known germline cancer-predisposing genes (RECQL4 and EXT2, respectively) and were not appeared in the DGV database, indicating both CNVs were probably damaging." (PMID 35860547, 2022). "If true, the number of genes that could potentially modify cancer proliferation via FGF signaling is much larger than currently appreciated, expanding from EXT1 and EXT2 to all aminoglycan synthesis genes." (PMID 30573688, 2018). "We selected six DplUSE-containing genes (KIF20A, EXT2, CLDN12, MBNL2, MED18, DKC1) from the 31 orthologous genes identified by the bioinformatic script that are common to human, mouse, and zebrafish and that have a relevant physiological function in malignant neoplasms." (PMID 41505098, 2026). "Although our study did not analyze the expression of Ext1 and Ext2 in cancers in detail, it is suggested that changes in the expression of Ext1 or Ext2 in cancers may contribute to the differences in cancer development in this study." (PMID 36809261, 2023).
autosomal dominant disease (3 papers, 2022 to 2024). Autosomal dominant form of disease. "In conclusion, the enigma of the EXT2 gene does not seem to fit well with a simple mechanism of haploinsufficiency for autosomal dominant diseases and requires further investigation." (PMID 40225915, 2024). "As stated in the introduction, the clinical diagnosis of the autosomal dominant disease of MO is often made without genetic testing, as in previous studies, a germline mutation in the EXT1 or EXT2 gene was found in almost 90% of cases." (PMID 35103870, 2022).
skeletal dysplasia (1 paper, 2024). Any Mendelian diseases that affects growth and development of the skeleton. "Therefore, the severity of skeletal dysplasia is correlated with the genotype, as patients with EXT1 mutations are more severely affected than those with EXT2 mutations." (PMID 39030613, 2024).
EXT2 also shares sentences with these, for which no sentence is quoted: lupus (6 papers); cartilage tumours (2); hepatocellular carcinoma (2); hereditary multiple osteochondromas (2); skeletal disease (2); squamous cell lung carcinoma (2); anaplastic astrocytoma (1); aniridia (1); astrocytoma (1); benign bone tumor (1); benign tumors (1); brain cancer (1); cartilage disease (1); crescentic glomerulonephritis (1); cystinuria (1); endothelial dysfunction (1); esophageal carcinoma (1); fibrodysplasia ossificans progressiva (1); gastric cancer (1); geleophysic dysplasia (1); genetic disorder (1); Hajdu-Cheney syndrome (1); Insulin resistance (1); Keipert syndrome (1); Maffucci syndrome (1); malignant peripheral nerve sheath tumor (1); Marfan syndrome (1); metachondromatosis (1); mixed connective tissue disease (1); multiple exostoses type II (1).
A further 11 diseases each share a sentence with EXT2 in 1 paper.